CXCR2 (C-X-C motif chemokine receptor 2)
Diseases named in the same sentence as CXCR2 in open-access papers (continued):
Sharing a sentence is not in itself a finding about the gene and the disease.
type 2 diabetes (2 papers, 2020 to 2024). "In accordance with this finding, our RNA-seq analysis revealed that the CXCR1 and CXCR2 genes were significantly upregulated in patients with type 2 diabetes compared with healthy controls." (PMID 32377527, 2020). "The effects of CXCR2 on glycocalyx shedding, and persistent renal inflammation was examined in a type 2 diabetic mouse model with Cxcr2 knockout specifically in endothelial cells (DKD-Cxcr2eCKO mice), as well as in glomerular endothelial cells (GECs), cultured in high glucose conditions." (PMID 38528533, 2024).
uveal melanoma (2 papers, 2007 to 2018). A melanoma derived from melanocytes of the uveal tract. "All 5 human uveal melanoma cell line cytospins stained positive for CXCL1, CXCL8, and their receptors CXCR2 and CXCR1 respectively." (PMID 17261188, 2007).
vasculitis (2 papers, 2018 to 2020). "In addition, expression of CXCR2 and CCR2 in the aortic root and coronary arteries is increased in CAWS-induced vasculitis mice, suggesting that CXCR2 promotes neutrophil recruitment and CCR2 controls monocyte infiltration." (PMID 33150252, 2020).
WHIM syndrome (2 papers, 2024 to 2025). "Our findings in CXCR2 LOF mice are consistent with previous reports in patients with WHIM syndrome indicating that CXCR4 antagonist treatment results in clinically significant improvements in peripheral blood neutrophil levels and reductions in infection rates." (PMID 41451234, 2025).
abdominal aortic aneurysm (1 paper, 2021). Enlargement and ballooning of the vessel that supplies arterial blood to the abdomen, pelvis and legs. "A mouse abdominal aortic aneurysm model wasestablished by embedding an Ang II pump (1000 ng/kg/min) in ApoE-/- mice.Ang II activated monocytes to express CXCR2(CD45+CD11+bF4/80+) during AAA formation." (PMID 33605308, 2021).
acute pancreatitis (1 paper, 2015). An acute inflammatory process that leads to necrosis of the pancreatic parenchyma. "We have shown that CXCR2 deficiency can interfere with NF‐κB‐dependent progression of acute pancreatitis." (PMID 25950520, 2015). "Many of the known molecular processes characterized in acute pancreatitis converge on CXCR2 signalling and stimulate CXC chemokine release." (PMID 25950520, 2015). "As before, we induced acute pancreatitis in wild‐type mice by seven hourly injections of caerulein, but this time we treated with CXCR2 pepducin, anti‐Ly6G antibody or control 1 h after the final injection." (PMID 25950520, 2015). "Acute pancreatitis was induced in cohorts of LysMCre, Cxcr2+/+ and LysMCre, Cxcr2fl/fl mice, and as above, animals were analysed 24 h after the first caerulein injection." (PMID 25950520, 2015). "Strikingly, Cxcr2−/− mice were strongly protected from tissue damage in models of acute pancreatitis, and this could be recapitulated by neutrophil depletion or by the specific deletion of Cxcr2 from myeloid cells." (PMID 25950520, 2015). "CXCR2 may therefore have considerable potential as a therapeutic target in the treatment of acute pancreatitis." (PMID 25950520, 2015). "Importantly, these data show that blocking CXCR2 or depleting neutrophils can significantly reduce pancreatic damage, even when it is initiated after the onset of acute pancreatitis." (PMID 25950520, 2015). "Next, in order to assess the potential therapeutic utility of CXCR2 inhibition in acute pancreatitis, we investigated whether inhibition of CXCR2 or neutrophil ablation could reverse or dampen ongoing pancreatic inflammation." (PMID 25950520, 2015).
acute pyelonephritis (1 paper, 2010). "Defects in expression of IL-8 receptors CXCR1 and CXCR2 have been associated with many infectious diseases, particularly acute pyelonephritis." (PMID 21151974, 2010).
adenomyosis (1 paper, 2024). The growth of endometrial tissue inside the muscular wall of the uterine corpus. "Additionally, the expression of IL-8 receptors, CXCR1 and CXCR2, is increased in adenomyosis lesions, suggesting that IL-8 and its receptors may be involved in the pathogenesis of adenomyosis." (PMID 39595579, 2024).
Allergy (1 paper, 2015). An allergy is an immune response or reaction to substances that are usually not harmful. "Chemokine receptors (CXCR1 and CXCR2) of activated mast cells receive cytokine (CCL5) signals, and stimulated mast cells migrate into the tissue to release histamine, lipid mediators, and other inflammatory cytokines and chemokines to cause serious allergy and inflammation." (PMID 25861366, 2015).
aspergillosis (1 paper, 2016). Aspergillosis is an infection, growth, or allergic response caused by the Aspergillus fungus. "We observed that mice with an attenuated host response, either due to Cxcr2 deficiency or due to corticosteroid immune suppression, were more susceptible to aspergillosis and the infection resulted in severe pulmonary inflammation." (PMID 27215684, 2016). "We investigated the role of CXCR2-mediated neutrophil recruitment in the development of hypoxia and inflammation during pulmonary aspergillosis by comparing Cxcr2−/− mice with wild-type mice." (PMID 27215684, 2016).
atrophic gastritis (1 paper, 2024).
biliary atresia (1 paper, 2017). A rare, biliary tract disease characterized by progressive obliterative cholangiopathy of the intra- and extrahepatic bile ducts, occurring in the embryonic/ perinatal period, leading to severe and persistent neonatal jaundice and acholic stool. "Although we do not yet know how A. lactolyticus or a related metabolite (such as butyrate) directly relates to Cxcr2 signaling to suppress the tissue injury, our data add a new biological dimension to the proposed pathogenic mechanisms of biliary atresia." (PMID 28763485, 2017). "In keeping with this possibility, we found a consistent enrichment with Anaerococcus in Cxcr2-/- mice resistant to the biliary atresia phenotype when compared to susceptible (diseased) mice." (PMID 28763485, 2017). "When treated with SMZ/TMP, Cxcr2-/- mice infected with RRV to induce experimental biliary atresia showed further enrichment of Corynebacterium, Anaerococcus and Streptococcus." (PMID 28763485, 2017). "We found that maternally administered antibiotics vertically affect the development of the gut-microbiome of neonatal Balb/c mice and protect them from the development of experimental biliary atresia in mice that lack a functional Cxcr2." (PMID 28763485, 2017). "Adult wild-type (WT) and Cxcr2-/- mice were fed a diet supplemented with sulfamethoxazole/trimethoprim (SMZ/TMP) during pregnancy and lactation, and their pups were injected intraperitoneally with rhesus rotavirus (RRV) within 24 hours of life to induce experimental biliary atresia." (PMID 28763485, 2017). "To more precisely link specific microbiome changes with the biliary atresia phenotype, we compared OTU data in the group of Cxcr2-/- mice without symptoms after RRV infection (here called “resistant”) with the group showing full phenotypic features of biliary atresia (here called “diseased”)." (PMID 28763485, 2017).
brain cancer (1 paper, 2025). A primary or metastatic malignant neoplasm affecting the brain. "Although CXCR2 expression was elevated in all brain cancer cell lines examined, CXCR1 appeared to be more selectively overexpressed in M059J and M059K cell lines up-regulated in GROα and/or IL-8." (PMID 40362634, 2025).
Cachexia (1 paper, 2020). Severe weight loss, wasting of muscle, loss of appetite, and general debility related to a chronic disease. "To identify unique mechanisms of immune cell recruitment to the brain and determine if inhibiting immune cells from infiltrating the brain attenuates cachexia, we treated OT-implanted tumor-bearing mice with either a CCR2 inhibitor (RS504393, Tocris) or CXCR2 inhibitor (SB225002, Tocris)." (PMID 32391790, 2020).
cardiomyopathies (1 paper, 2023). "In silico analysis showed several of these piRNAs were computationally predicted to target and potentially regulate expression of genes including SMAD2, EGR1, ICAM1, CX3CL1, and CXCR2, which have been implicated in parasite infection, pathogenesis, and various cardiomyopathies." (PMID 36936778, 2023).
Carditis (1 paper, 2013). "The interaction between CXCL1 and CXCR2 is critical for mediating leukocyte recruitment in many diseases such as Lyme Arthritis, Carditis and experimental brain abscesses." (PMID 23967336, 2013).
cerebral infarction (1 paper, 2021). An ischemic condition of the brain, producing a persistent focal neurological deficit in the area of distribution of the cerebral arteries. "Brain tissues of MCAO model rats showed significantly increased cerebral infarction areas, cerebral water, neuronal apoptosis, and activated CXCL1/CXCR2/NF-κB signaling, but these effects were alleviated by intraventricular injection of miR-532-5p agomir." (PMID 33867350, 2021).
cerebral palsy (1 paper, 2025). A group of disorders affecting the development of movement and posture, often accompanied by disturbances of sensation, perception, cognition, and behavior. "Using a model for cerebral palsy, newborn rats suffering hypoxic-ischemic injury were given a CXCR2 antagonist in their investigations." (PMID 40715588, 2025). "According to the findings, CXCR2 immunomodulation might not aid in lowering the cognitive abnormalities connected with cerebral palsy, even if it may preserve white matter integrity and enhance motor performance." (PMID 40715588, 2025).
cervical tumors (1 paper, 2023). "Our study aimed to investigate the influence of inhibiting IDO-1 and CXCR-2 on cervical tumor growth." (PMID 37626777, 2023). "Considering that the combined inhibition of IDO-1 and CXCR-2 (K14E7E2 + CT) exhibited a more significant effect in reducing cervical tumor areas compared to single-drug treatment in mice that developed CIN-III/CC (K14E7E2), we decided to utilize this regimen for our subsequent experiments." (PMID 37626777, 2023). "Our results revealed that combined inhibition of IDO-1 and CXCR-2 significantly reduces the areas of cervical tumors (from 196.0 mm2 to 58.24 mm2 in R1 and 149.6 mm2 to 52.65 mm2 in R2), accompanied by regions of moderate dysplasia, decreased papillae, and reduced inflammation." (PMID 37626777, 2023).
chronic lung disease (1 paper, 2022). According to the definitions of the American and British Thoracic Societies, including pulmonary functional tests, X-rays, and CT scans for items such as fibrosis, bronchiectasis, bullae, emphysema, nodular or lymphomatous abnormalities. "CXCR2 is important in the pathology of a wide range of chronic lung diseases, and modulation of CXCR2 function is considered a possible therapeutic strategy." (PMID 35163035, 2022).
colon adenocarcinoma (1 paper, 2015). "We have reported previously that the mean expression of CXCR2 was decreased in dissected mucosal tissues of human colon adenoma, primary colon adenocarcinoma and metastasis." (PMID 26104296, 2015).
colonic disease (1 paper, 2022). "This study suggests that inhibiting CXCL8/CXCR2 should be investigated in patients with right‐sided colonic disease and stroma‐rich tumours." (PMID 35879507, 2022).
congenital neutropenia (1 paper, 2026). "This case expands the mutational and phenotypic spectrum of CXCR2-related congenital neutropenia and highlights the value of genetic testing for infants with unexplained chronic neutropenia and recurrent infections." (PMID 42292363, 2026).
corneal infection (1 paper, 2024). A viral or bacterial infectious process affecting the cornea. "As well, the receptor for these CXC chemokines, CXCR2, which was significantly upregulated in the cornea and conjunctiva of the corneal infection patients, plays a significant role in the pathogenesis of bacterial keratitis." (PMID 38694515, 2024).
Crush Syndrome (1 paper, 2022). Severe systemic manifestation of trauma and ischemia involving soft tissues, principally skeletal muscle, due to prolonged severe crushing. "The expression levels of inflammatory cytokines and chemokines (e.g., TNFα, IL-6, CXCL1, CXCL2, CXCR2, CCL2) in crush syndrome were significantly suppressed in TPEN-treated group." (PMID 36114355, 2022).
diabetic foot ulcers (1 paper, 2025). "Since these mediators play a critical role in wound healing, they may be an attractive target in diabetic foot ulcers to promote healing by increasing MAPK13 and decreasing TSP1 and CXCR2 in chronic nonhealing wounds." (PMID 41514867, 2025).
diabetic proliferative retinopathy (1 paper, 2023). "Therefore, the PGF2α‐mediated expression of ELR+ CXC chemokines in ECs contributes to the pathogenesis of diabetic proliferative retinopathy via CXCR2." (PMID 36511116, 2023).
diabetic retinopathy (1 paper, 2025). "Neutrophils respond to CXCL1 through activation of CXCR2, and this cytokine is elevated in the retinas of individuals with diabetic retinopathy." (PMID 39875729, 2025).
endometrioid adenocarcinoma (1 paper, 2022). An adenocarcinoma characterized by the presence of malignant glandular epithelial cells resembling endometrial cells. "In addition, the expression of MYC and CXCR2 in the tumor related to non-endometrioid adenocarcinoma and reduced the risk of recurrence, respectively, and higher NR5A2 expression in tumor-adjacent tissue increased the risk of death." (PMID 36140779, 2022).
Failure to thrive (1 paper, 2025). Failure to thrive (FTT) refers to a child whose physical growth is substantially below the norm. "Unfortunately, Cxcr2-KO mice exhibit failure to thrive when neutrophil recruitment was knocked out and/or there were compensation phenotypes for neutrophil recruitment; importantly, surgical procedures were not well tolerated." (PMID 39836475, 2025).
food allergy (1 paper, 2024). Gastrointestinal disturbances, skin eruptions, or shock due to allergic reactions to allergens in food. "The mRNA expression of Cxcr2 (a chemokine receptor of mast cell) in the jejunum in mice with food allergy was also inhibited by melatonin." (PMID 39040920, 2024).
HCMV infection (1 paper, 2025). "Together with the network analyses and cell contraction assays, IL-8/CXCR2 using Cdc42 appeared to play crucial roles in HTMCs dynamics after HCMV infection." (PMID 40353220, 2025). "Our study highlighted the distinct profiles of the Rho family GTPases-Cdc42, Rho-A, and Rac1 following HCMV infection, especially in the context of IL-8/CXCR2 signaling." (PMID 40353220, 2025). "Our network analysis of the CXCR2-dependent genes after HCMV infection indicated that the Rho-kinase pathway is operative for CXCR2-mediated signaling." (PMID 40353220, 2025). "This contraction was observed after HCMV infection through CXCR2." (PMID 40353220, 2025). "Our findings emphasize the unique contributions of the coordinate activation of Cdc42 and Rac1, especially in CXCR2 and CCR2-mediated activation after HCMV infection." (PMID 40353220, 2025). "HCMV infection also induced cell contraction that was dependent on CXCR2, but not on CCR2, and it involved the activation of Rac1/Cdc42." (PMID 40353220, 2025). "Thus, CXCR2 and CCR2 play different roles in the activation of Rho GTPases after HCMV infection." (PMID 40353220, 2025).
hearing loss (1 paper, 2023). "To better establish a role of CXCR2 in mediating cisplatin-induced hearing loss, we examined whether knockdown of CXCR2 mRNA protects against cisplatin-induced hearing loss." (PMID 37063917, 2023). "Trans-tympanic administration of SB225002, a chemical inhibitor of CXCR2 (receptor target for CXCL1) reduced immune cell migration, protected against cisplatin-induced hearing loss and preserved hair cell integrity." (PMID 37063917, 2023). "Thus, inhibiting CXCR2 could serve as a novel method for treating cisplatin-induced hearing loss." (PMID 37063917, 2023).
hypertensive heart disease (1 paper, 2025). Abnormal enlargement of the heart resulting from long-standing hypertension. "This study concluded that the inhibition of CXCL1 and/or CXCR2 might be a promising therapeutic approach for treating hypertensive heart diseases." (PMID 40109339, 2025).
IgA nephropathy (1 paper, 2013). "To further evaluate the involvement of CXCR2 in podocyte loss in IgA nephropathy, we investigated expression of CXCR2 in urine exfoliated podocytes in 19 IgAN patients." (PMID 24023680, 2013). "Therefore, the expression of CXCR2 on urine exfoliated podocytes supported its involvement in podocyte loss in IgA nephropathy." (PMID 24023680, 2013).
infectious colitis (1 paper, 2024). A viral or bacterial infectious process affecting the large intestine. "The reciprocal regulation of CXCR2 and CCR3/CCR10 in neutrophils and each receptor’s contribution to neutrophil migration and retention during infectious colitis requires further study." (PMID 39193987, 2024).
intracranial aneurysm (1 paper, 2022). "The study aimed to assess the NF-κB p65 subunit and the GRO-α chemokine and its receptor CXCR2 concentrations in unruptured intracranial aneurysm patients (UIA, n = 25) compared to individuals without vascular changes in the brain (n = 10)." (PMID 36494512, 2022).
invasive candidiasis (1 paper, 2012). "In fact, Cxcr2-deficient mice were previously reported to have impaired ability to control Candida proliferation in the kidney and other organs after invasive candidiasis, but accumulation of neutrophils in these tissues was not defined in that study." (PMID 22916017, 2012).
invasive carcinoma (1 paper, 2020). A carcinoma that is not confined to the epithelium, and has spread to the surrounding stroma. "Patients were divided into three equal groups according to their levels of CXCR2 expression (low, medium and high) in invasive carcinoma and analyzed for TTR." (PMID 32727083, 2020).
invasive ductal carcinomas (1 paper, 2012). "Additionally, human invasive ductal carcinoma (IDC) tissue arrays were used to confirm the hPTTG1/CXCR2/p21 axis established in vitro." (PMID 22789011, 2012).
itch (1 paper, 2023). "In cheek itch models, we revealed that the CXCR2 shRNA virus caused a significant reduction in itching responses induced by CQ (107 ± 17 versus 38 ± 7, p < 0.01) and histamine (115 ± 7 versus 72 ± 11, p < 0.01)." (PMID 37953876, 2023). "Our results revealed a significant up-regulation of CXCR2 mRNA and protein expressions in the primary sensory neurons of TG in response to itch stimuli." (PMID 37953876, 2023).
Jaundice (1 paper, 2017). Yellow pigmentation of the skin due to bilirubin, which in turn is the result of increased bilirubin concentration in the bloodstream. "The frequency of jaundice was lower in neonatal Cxcr2-/- mice 14 days after RRV when their mothers received SMZ/TMP (100% in regular diet vs. 52.4% in SMZ/TMP, P < 0.0001), along with improved survival when compared to regular diet (0% in regular diet vs. 55.8% in SMZ/TMP, P < 0.0001)." (PMID 28763485, 2017).
kidney damage (1 paper, 2023). "Up-expression of CXCL1 exacerbates fibrosis mediated kidney damage, and inhibition of CXCL1 - CXCR2 shaft can greatly relieve kidney inflammation." (PMID 37266443, 2023).
leprosy (1 paper, 2021). Leprosy is a chronic infectious disease affecting primarily the skin and peripheral nervous system. "Several other mRNAs, such as CXCR2, which was also differentially expressed in the PBMCs of leprosy patients, are not validated." (PMID 34993156, 2021).
lipodystrophy (1 paper, 2024). A congenital or acquired disorder characterized by abnormal loss or redistribution of the adipose tissue in the body. "For the first time, our research revealed that ibuprofen downregulates CXCR1 and CXCR2 in PBMCs of lipodystrophy, leading to improvements in glucose and lipid metabolism associated with lipodystrophy." (PMID 38989000, 2024).